ALDH2 (aldehyde dehydrogenase 2 family member)
Diseases named in the same sentence as ALDH2 in open-access papers (continued):
Sharing a sentence is not in itself a finding about the gene and the disease.
Fanconi anemia (24 papers, 2014 to 2025). Fanconi anemia (FA) is a hereditary DNA repair disorder characterized by progressive pancytopenia with bone marrow failure, variable congenital malformations and predisposition to develop hematological or solid tumors. "Malformations in multiple anatomic locations were observed more frequently in ALDH2-deficient patients diagnosed with Fanconi anemia in Japanese patients." (PMID 35749303, 2022). "Concomitant inactivation of the Fanconi anemia DNA repair pathway and the aldehyde catabolism enzyme ALDH2 results in HSC chromosome damage and loss." (PMID 30306211, 2019). "Notably, the failure to detoxify endogenously produced aldehydes in patients with a combination of the ADH5 allele and ALDH2 causes Fanconi anemia, underscoring the critical role of ALDH in the hematopoietic system." (PMID 38226171, 2024). "One example is the DNA repair‐deficient disorder Fanconi anemia with the ALDH2 variant." (PMID 36345163, 2023). "In Asian populations, a functional ALDH2 polymorphism (ALDH2; rs671, Glu504Lys) is highly prevalent and suspected to be related to an accelerated progression of bone marrow failure and malignant transformation in Fanconi anemia patients." (PMID 34830855, 2021). "Failure of this genome preservation mechanism might explain why birth defects and bone marrow failure occur in Fanconi anemia, and may have implications for fetal well-being in the many women in Southeast Asia that are genetically deficient in ALDH2." (PMID 25155611, 2014). "FA has emerged as a fundamental contributor to human disorders such as Fanconi anemia, Cockayne syndrome, and AMeDS, which are caused by mutations in FANC genes, CSB or CSA, and ADH5 and ALDH2, respectively." (PMID 38894680, 2024). "Recent evidence also pointed out that ALDH2 dysfunction is relevant to Fanconi anemia, pain, osteoporosis, and human aging." (PMID 39416436, 2024). "Detoxifying enzymes like ALDH2 provide primary protection against aldehydes, whereas the Fanconi anemia pathway is an essential mechanism for counteracting those damages." (PMID 33573309, 2021). "The level of activity of the Fanconi Anemia pathway appears to be sufficient to sustain primordial germ cell numbers, at least in inbred mice, since single mutants of Aldh2 and Adh5 have wild-type levels of primordial germ cells by embryonic day 12.5." (PMID 33500205, 2021). "This seems to be true not only for solid tumors but also for leukemogenesis; the involvement of ALDH (including ALDH2) for progression of preleukemic Fanconi anemia to bone marrow failure/AML is suggested both by animal models and clinical studies." (PMID 33349623, 2020). "A decrease in the ALDH2-GA or ALDH2-AA genotype was reported to accelerate the conversion of Fanconi anemia to MDS/AML." (PMID 32373530, 2020). "Knockout of ALDH2 in a murine model of Fanconi anemia (FA), Aldh2(−/−)Fancd2(−/−) mice spontaneously develop acute leukemia." (PMID 29516013, 2018). "Knockout of ALDH2 in Fanconi anemia pathway-deficient keratinocytes did not have a significant synthetic lethal effect in our study." (PMID 41292832, 2025). "Similarly, the BRCA‐related Fanconi anemia gene and ALDH2 are required to sustain cell growth in leukemic cells." (PMID 36345163, 2023). "In primordial germ cells, endogenous DNA crosslinks that are substrates for Fanconi Anemia-mediated repair may derive from reactive aldehydes, since Fanca becomes critical in Aldh2 and Adh5 mutants that accumulate endogenous reactive aldehydes." (PMID 33500205, 2021). "High levels of reactive aldehydes overwhelm the detoxification capacity of ALDH2/ADH5 and result in DNA interstrand crosslinks (ICLs) that require functional Fanconi anemia pathway for repair." (PMID 40854122, 2025).
Fanconi anemia (continued). "Tier 1 involves aldehyde detoxification enzymes (ALDH2 and ADH5) followed by tier 2 Fanconi anemia DNA damage repair pathways to repair aldehyde-induced DNA damage." (PMID 38963759, 2024). "HSCs produce genotoxic formaldehyde that requires protection by the detoxification enzymes ALDH2 and ADH5 and the Fanconi anemia (FA) DNA repair pathway." (PMID 37348497, 2023). "Both in mice and humans, in the absence of the protective role of the Fanconi anemia DNA repair pathway and the activity of an isoform of aldehyde dehydrogenases (ALDH2), ethanol’s genotoxic effect results in severe depletion of the HSCs pool." (PMID 34638483, 2021). "These adverse effects can be scavenged by detoxifying enzymes, which have been the main focus of recent research in patients of a rare hereditary Fanconi anemia and animals with impaired expression of the DDR gene FANCD2 and the detoxifying enzymes ALDH2 and ADH5." (PMID 33573309, 2021).
alcohol abuse (22 papers, 2016 to 2026). The use of alcoholic beverages to excess, either on individual occasions ("binge drinking") or as a regular practice. "In contrast, the markedly decreased risk of alcohol‐induced mental disorders (OR = 0.13), alcohol dependence syndrome (OR = 0.17), and alcohol abuse (OR = 0.34) was statistically significant for the ALDH2 rs671 A allele carriers (p < 0.001)." (PMID 35670037, 2023). "Alcohol abuse and chronic use, the consumption of aged beer, and ALDH2 deficiencies can synergically enhance overall acetaldehyde body burdens, increasing potential genotoxic and carcinogenic effects." (PMID 36430619, 2022). "Disulfiram (DSF) or antabuse was developed over 50 yr ago to treat alcohol abuse and works by inhibiting ALDH2, mimicking the ALDH2*2 mutation in humans." (PMID 35414258, 2022). "Most patients with alcohol abuse or dependence with inactive ALDH2 alleles were heterozygous while homozygous lys/lys was rarely found, although it was often observed in controls." (PMID 32143280, 2020). "Variants in genes encoding ALDH2 are important determinants of risk for alcohol abuse or dependence and to a lesser extent for cirrhosis, especially in Asian populations." (PMID 32143280, 2020). "Other risk factors include pattern of alcohol consumption, parental history of alcohol abuse, male gender, and mutation of ALDH2." (PMID 30467601, 2019). "These analyses have revealed that people carrying the ALDH2*2 allele are protected against alcohol abuse, especially those of Han Chinese and/or Japanese ethnicities." (PMID 27159808, 2016). "In other words, our findings suggest that alcohol abuse may predispose individuals with the ALDH2*2 allele to AF." (PMID 32932651, 2020). "The reduced-activity ALDH2*2 allele most commonly is found in people of East-Asian descent (i.e., Chinese, Japanese, and Korean), meaning these subgroups theoretically are most protected against alcohol abuse." (PMID 27159808, 2016). "Whole‐exome sequencing of 83 alcohol use disorder patients identified 106,525 SNVs and 19,826 InDels, revealing six genes (CNTNAP3, ZNF683, ALDH2, CCHCR1, ZNF45, ESRRA) with deleterious mutations through comprehensive bioinformatics analysis." (PMID 40730494, 2025). "The ALDH2*1 allele was found as a risk factor for alcohol abuse and alcohol cirrhosis, and combined genotypes of ADH1B rs1229984, ADH1C rs698 and ALDH2 rs671 with non‐acetaldehyde accumulation increase alcohol cirrhosis risk." (PMID 40730494, 2025). "Genes such as ADH1B and ALDH2 have been shown to be protective in Asian populations, while ADH1C has been shown to increase the risk for alcohol use disorder." (PMID 38359015, 2024). "Traditionally, the research focus on ALDH2*2 has centered on its implications in alcohol metabolism, linking it to increased risks of alcohol-related cancers, cardiovascular diseases, and alcohol use disorders." (PMID 38396862, 2024). "In contrast, the notably decreased risks of alcohol‐induced mental disorders (OR = 0.13), alcohol dependence syndrome (OR = 0.17), and alcohol abuse (OR = 0.34) were statistically significant in the ALDH2 rs671 carriers (p < 0.001)." (PMID 35670037, 2023). "The inactive ALDH2*2 (+) genotype (*1/*2 or *2/*2), resulting in acetaldehyde accumulation, provides a protective effect against alcohol use disorder." (PMID 35670037, 2023). "Aldehyde dehydrogenase-2 (ALDH2) is a crucial enzyme participating in intracellular aldehyde metabolism and is acknowledged as a potential therapeutic target for the treatment of alcohol use disorder and other addictive behaviors." (PMID 37959744, 2023). "ALDH2 not only plays an important role in the prevention and treatment of alcohol abuse, but also widely participates in the key regulatory pathways of diseases related to apoptosis, aging, fibrosis, and neurodegeneration." (PMID 35269824, 2022).
alcohol abuse (continued). "The high prevalence of the ALDH2*2 and ADH1B*2 alleles in a large percentage of Asian subgroups has been studied as a potential protective factors against alcohol abuse, yet some individuals who possess these genes still engage in problematic alcohol use." (PMID 27159808, 2016). "Inhibition of ALDH2 is a well-known pharmacological intervention as a treatment for alcohol abuse." (PMID 37760911, 2023). "It is worth noting that the protective effect of the ALDH2 rs671 GA/AA genotypes against alcohol abuse may be a predictive factor of certain psychosocial issues." (PMID 35670037, 2023). "Although the ADH1B*2 and ALDH2*2 alleles both can serve as protective factors against alcohol abuse, they do not seem to eliminate alcohol consumption altogether." (PMID 27159808, 2016). "Genes related to serotonin and dopamine biosynthesis, as well as Aldh2, were also impacted, linking CBD’s effects in hypothalamic neurons to potential benefits in managing alcohol use disorders." (PMID 40335839, 2025). "Additionally, CBD-influenced genes associated with serotonin and dopamine biosynthesis, including the Aldh2 gene, link CBD’s action in hypothalamic neurons to its proposed benefits in treating alcohol use disorders." (PMID 40335839, 2025). "The ATA has a moderation effect on the relationship between ALDH2 rs671 and AUD, which means that more extent of positive attitude to alcohol drinking may contribute to less benefits of genetic inheritance for avoidance the alcohol abuse." (PMID 40857241, 2025).
head and neck cancer (22 papers, 2014 to 2025). A primary or metastatic malignant neoplasm affecting the head and neck. "Prolonged alcohol consumption among individuals with the ALDH2 variant significantly amplifies the risk of developing alcohol-related cancers, such as esophageal and head or neck cancers, by several times compared to those with active ALDH2." (PMID 38796304, 2024). "Specifically, the ALDH2*2 allele with a slower AcAH-metabolizing capacity represents an increased risk of alcohol-related cancers such as esophageal and head and neck cancers." (PMID 36831600, 2023). "On the other hand, ALDH2 expression has been shown to be downregulated in breast, lung, esophageal, and head and neck cancers, and this reduction in ALDH2 expression has been linked to a poor prognosis of cancer patients." (PMID 36831600, 2023). "In Japan, Taiwan, and China, ALDH2 heterodeficient drinkers have a particularly high risk for esophageal and head and neck cancer, and ALDH2 heterozygous deficiency is strongly associated with multiple carcinogenesis and juvenile carcinogenesis." (PMID 36028843, 2022). "In fact, there is ample evidence showed that subjects with an inactive form of ALDH2 (heterozygous for ALDH2 mutation) have an increased risk of developing various types of head and neck cancers as a consequent of intense exposure to acetaldehyde." (PMID 29299137, 2017). "Previously, ALDH2*2 mutation was shown to increase susceptibility to upper respiratory tract and head and neck cancers." (PMID 28532411, 2017). "Overall, studies have indicated that ALDH2 polymorphism can modulate the association between alcohol drinking and head and neck cancer risk." (PMID 28253921, 2017). "It is well known that the ALDH2 rs671 GA/AA genotypes may lead to a higher risk of head and neck cancer with alcohol ingestion." (PMID 35670037, 2023). "Nonsynonymous SNPs in ADH1B (rs671) and ALDH2 (rs1229984) and head and neck cancer, oro‐/hypopharyngeal cancer and oral squamous cell carcinoma in univariate analysis." (PMID 37706329, 2023). "Inactive heterozygous ALDH2 alleles cause a deficiency of the enzyme and were shown to increase the risk of esophageal squamous cell carcinoma (SCC) and metachronous head and neck cancer." (PMID 28562351, 2017). "The impact of the ALDH2 rs671 G>A polymorphism on alcohol induced carcinogenesis has been identified in published studies of cancers of the UADT, including head and neck cancers and OSCC." (PMID 29254255, 2017). "Individual with the fast ADH1B genotype, the head and neck cancer risk associated with drinking alcohol was raised as compared with those with the slow/nonfunctional ALDH2 genotypes." (PMID 35670037, 2023). "Three of the four studies published after the meta-analysis all showed a synergistic interaction between ALDH2*2 allele and alcohol drinking to increase head and neck cancer risk and only one study did not observe such interaction." (PMID 28253921, 2017). "Genetic factors such as ADH/ALDH2 polymorphism, lack of ALDH2 or low levels of expression of ALDH2 and alcohol drinking habits were reported to be associated with higher risk of head and neck cancer." (PMID 26473489, 2015). "A prospective and functional study is needed to provide more precise information about the role and prognostic aspect of ALDH2 and SOD2 genes in head and neck cancer." (PMID 28841898, 2017). "Nevertheless, in another study, head and neck cancer patients with the fast ADH1B and the slow/nonfunctional ALDH2 genotypes had the poorest overall survival." (PMID 35670037, 2023).
myocardial ischemia (22 papers, 2014 to 2026). A disorder of cardiac function caused by insufficient blood flow to the muscle tissue of the heart. "One study on patients with ST-elevation myocardial infarction indicated that the ALDH2 rs671 (A) allele was associated with more severe myocardial ischemia/reperfusion injury only in male patients." (PMID 39290715, 2024). "Previous study shows aldehyde dehydrogenase 2 (ALDH2) plays a critical role in myocardial protection against ischemia, and down-regulation of ALDH2 expression is associated with exacerbated myocardial ischemia injury." (PMID 25629048, 2015). "Additionally, ALDH2 polymorphism has been linked to increased susceptibility to myocardial ischemia/reperfusion (I/R) injury, a major contributor to adverse outcomes in patients with ACS." (PMID 41551908, 2026). "ALDH2 plays a crucial role in the bioactivation of nitroglycerin by catalyzing its conversion to nitric oxide (NO), a potent vasodilator that alleviates myocardial ischemia." (PMID 40979589, 2025). "Experiments have shown that both protein kinase C ε (PKCε) agonists and ethanol can increase ALDH2 during cardiac ischemia in mice." (PMID 34799616, 2021). "ALDH2 has a beneficial effect in myocardial ischemia/reperfusion (I/R) injury, possibly through the induction of autophagy during ischemia and a reduction of autophagy during reperfusion." (PMID 34025411, 2021). "We previously confirmed that ALDH2 can inhibit myocardial ischemia/reperfusion injury by regulating mitophagy." (PMID 34025411, 2021). "Recent research has shown that local RAS activation, Ang II generation, and NE release are inhibited by activating MC GPCRs and the consequent stimulation of the PKCε/ALDH2 pathway, leading to ventricular arrhythmias in myocardial ischemia." (PMID 34512339, 2021). "The cardioprotective and neuroprotective role of ALDH2 in myocardial ischemia–reperfusion has been demonstrated, with recent evidence showing that ALDH2 inhibition alters endothelial functions along with a deterioration of bioenergetic functions." (PMID 34069402, 2021). "Later, reports gradually came that ALDH2 is of protective effect for alcoholic heart injury, myocardial ischemia, and coronary vessels, identifying the protective role of ALDH2 against heart diseases." (PMID 32626739, 2020). "Prior studies has provided evidences that ALDH2 protects against myocardial ischemia/reperfusion (I/R) injury by removing toxic aldehydes such as 4-HNE in animal models of myocardial ischemia." (PMID 32160861, 2020). "Pretreatment with the specific agonist of ALDH2 Alda-1 can improve myocardial ischemia/reperfusion injury in rats by upregulating the expression of ALDH2 and play an important protective role in high glucose-induced myocardial cell injury." (PMID 29129988, 2017). "ALDH2 is phosphorylated by PKCε and its activity is negatively correlated with infarct size in animal model of cardiac ischemia." (PMID 27575855, 2016). "As a key enzyme against myocardial ischemia injury, ALDH2 is also regulated under some other potential mechanisms which could induce the declination of its expression or enzyme activity." (PMID 25629048, 2015). "Despite its well‐recognized role in ethanol metabolism, previous studies have shown that ALDH2 plays a critical protective role against myocardial injuries, including septic cardiomyopathy, alcoholic cardiomyopathy, diabetic cardiomyopathy, and myocardial ischemia–reperfusion injury." (PMID 41542286, 2026).